MTOR (mechanistic target of rapamycin kinase)
Diseases named in the same sentence as MTOR in open-access papers (continued):
Sharing a sentence is not in itself a finding about the gene and the disease.
glioma (continued). "There are approximately twenty current clinical studies using mTOR inhibitors for the treatment of gliomas." (PMID 27158244, 2016). "Several studies have reported AMPK-independent effects of Compound C, which seems to involve antagonism of mTOR pathway in T cells and multiple mechanisms in human gliomas." (PMID 27602497, 2016). "In radioresistant glioma cells, treatment with the mTOR inhibitors rapamycin and PP242 can enhance radiosensitivity by potently and persistently activating the autophagic flux." (PMID 26830677, 2016). "In this study, the major novel findings were that miR-129 is a new inducer of autophagy both through mTOR signaling and upregulation of Beclin-1 by targetedly suppressing Notch-1 in glioma cell lines." (PMID 26824182, 2016). "The 2, 3-bis (4-hydeoxyphenyl)-propionitrile (DPN) activates mTOR pathway in EAE mice, while liquiritigenin inhibits mTOR activation in glioma cells." (PMID 27863380, 2016). "A radioresistant phenotype has also been observed in glioma cells through an mTOR-dependent autophagy." (PMID 27043632, 2016). "The mTOR kinase is required for the survival and maintenance of the stem cell state in NSCs and glioma cancer stem cells." (PMID 28018177, 2016). "Taken together, these studies demonstrated the expression of TELO2 correlated with mTOR expression in human gliomas." (PMID 27329594, 2016). "PI-103, the most potent novel HIF-1 inhibitor among the PI3K pathway inhibitors tested in this study, is a dual PI3K and mTOR inhibitor with anti-proliferative activity in leukemia, hepatocellular carcinoma, and glioma cells." (PMID 26882567, 2016). "The protein level of TELO2 significantly increased correlates with the mTOR expression in human glioma cell lines including U118MG, GBM8401, U87MG, and LN229 as compared with normal brain tissue." (PMID 27329594, 2016). "Mammalian target of rapamycin (mTOR) signaling is often dysregulated and hyper-activated in glioma, which mediates tumorigenesis, progression and chemoresistance." (PMID 27295037, 2016). "The mTOR pathway has been reported to be involved in bladder cancer, metastatic kidney cancer, hepatocellular carcinoma and glioma." (PMID 26259252, 2015). "Conversely, targeting of the mutant RTK/PI3K/Akt/mTOR signaling pathway leads to consistent reduction in the invasion and migration by VM channels in U251 glioma cells." (PMID 26085929, 2015). "We further assessed the biological significance of miR-199a-3p in the regulation of mTOR expression in glioma cells." (PMID 25854175, 2015). "Recent study revealed that PI3K/Akt/mTOR signal pathway would be commonly activated in human glioma cells." (PMID 26648842, 2015). "At the beginning of the simulation (t = 0h), when a glioma cell is randomly searching for a better environment, both miR-451 and mTOR levels are low and the AMPK level is high due to the relatively low glucose level in the environment." (PMID 25629604, 2015). "Imipramine has already been demonstrated to reduce cell proliferation, inhibit the PI3K/Akt/mTOR signaling pathway and to induce autophagic cell death in human glioma cells." (PMID 26530050, 2015). "Hyperactivation of downstream phosphatidylinositol 3-kinase (PI3K)/AKT/mammalian target of rapamycin (mTOR) pathway is another common occurrence of human glioma." (PMID 25886314, 2015). "In our study, glioma cells express VEGFR-2 upon loss of PTEN function through activation of AKT and mTOR." (PMID 25682871, 2015). "Inhibitors of mTOR, for example, NVP-BEZ235 and miRNAs, block the AKT/mTOR signaling pathway and suppress tumor cells’ growth in many malignant tumors, including glioma." (PMID 25854175, 2015). "The expression of mTOR in glioma samples was higher combined with normal brain tissues and increased with the increasing degree of malignancy in glioma (low-grade glioma vs. high-grade glioma, P < 0.01)." (PMID 25854175, 2015). "Results from our study implied that miR-199a-3p plays a critical role as a kind of inhibitor of mTOR in glioma." (PMID 25854175, 2015).
glioma (continued). "In glioma cells the molecular mechanism underlying GOLPH3 function in migration and invasion requires mTOR and one of its effectors, the transcription/translation regulatory protein Y-box binding protein-1 (YB1)." (PMID 25691054, 2015). "We found that Tspan8 expression level is high in both malignant glioma tissues and in several human glioma cell lines, where it formed a complex integrin α3 and rictor, the latter is a key component of mammalian target of rapamycin (mTOR) complex 2 (mTORC2)." (PMID 25761241, 2015). "Targeting both PI3K and mTOR has been shown to be essential for the elimination of feedback activation in glioma cells, and results in the inhibition of glioma cell proliferation." (PMID 25431423, 2015). "VEGFR-2-positive glioma cells were exclusively PTEN-deficient suggesting the requirement of PTEN loss and subsequent activation of the PI3K/AKT/mTOR signaling pathway." (PMID 25682871, 2015). "CPZ inhibited cell-cycle progression in rat glioma C6 cells by inducing p21Waf/Cip1/Egr1 expression and induced autophagic cell death by inhibiting the AKT/mTOR pathway in human glioma U87-MG cells." (PMID 26363315, 2015). "A sub-analysis by KEGG signalling pathways revealed that SLC16A7 co-expressed genes are grouped in pathways associated with PCa, colorectal cancer, renal cell carcinoma, leukemia, melanoma, glioma and mTOR signalling pathway among others." (PMID 26035357, 2015). "The effective role miR-199a-3p played in glioma can be attributed to the suppression of the AKT/mTOR signaling pathway." (PMID 25854175, 2015). "Golgi phosphoprotein 3 (GOLPH3) is also found to be upregulated in gliomas and involved in glioma cell migration and invasion via the mammalian target of rapamycin (mTOR)-Y-box binding protein-1 (YB1) pathway." (PMID 26098895, 2015). "PI3K pathway activation also differed based on IDH status: upstream changes such as PTEN deletion or AKT gain were more common in IDHwt gliomas and MTOR gain was significantly less common (p = 2 × 10−7, 0.002, and 1 × 10−5, respectively)." (PMID 26091668, 2015). "The inhibition of mTOR cascade reaction pathway was also involved in the synergistic anti-glioma effect of niclosamide in combination with emozolomide." (PMID 26648842, 2015). "MiR-199a-3p in glioma cell lines has effects similar to the tumor suppressor gene on cellular proliferation via the AKT/mTOR signaling pathway." (PMID 25854175, 2015). "In glioma cells, ROS induce autophagy by inhibiting mTOR in a BNIP3-dependent manner (BNIP3: BCL2/adenovirus E1B 19 kDa protein-interacting protein 3)." (PMID 25803050, 2015). "Recent studies on the glioma kinome have identified several deregulated pathways that converge and activate mTOR." (PMID 25051975, 2014). "The subsequent increase in the ratio of M1 microglial cells bearing cytotoxic and perhaps tumoricidal properties is a mechanism of potential interest in light of a possible clinical development of mTOR inhibitors in the treatment of human glioma." (PMID 25051975, 2014). "At present, ClinicalTrials.gov lists 299 ongoing studies on mTOR and cancer, 17 being studies on mTOR and glioma, mostly testing the dual inhibition of mTORC1 and mTORC2." (PMID 25051975, 2014). "Here we show that the inhibition of mTOR polarizes glioma-activated microglial cells towards the M1 phenotype, with cytotoxic activities, preventing the induction of the M2 status that promotes tumor growth." (PMID 25051975, 2014). "In this study we evaluated the effects of mTOR inhibitors on microglial polarization in experimental models of glioma-microglia interaction." (PMID 25051975, 2014). "The PI3K/AKT/mTOR pathway is central to the biology of glial tumors but also contributes to neural development." (PMID 24936516, 2014). "Thereafter, we assessed the effect of mTOR inhibitors on microglia viability in cells exposed to glioma-conditioned media." (PMID 25051975, 2014).
glioma (continued). "Recently published studies show that XL765, a dual PI3K/mTOR inhibitor, has potent activity in an intracranial xenograft mouse model of high-grade glioma." (PMID 23717811, 2013). "This is the first in vivo demonstration of combinatorial activity of an mTOR inhibitor with a BRAF inhibitor in gliomas, and will inform future clinical trials in pediatric brain tumor patients." (PMID 23717811, 2013). "Another major signaling cascade that plays a role in pediatric glioma pathogenesis is the PI3-kinase (PI3K)/mTOR pathway, known to be upregulated in the majority of high- and low-grade pediatric gliomas." (PMID 23717811, 2013). "In vitro and in vivo data support the use of MEK or mammalian target of rapamycin (mTOR) inhibitors in low-grade gliomas expressing this translocation." (PMID 23717811, 2013). "In sporadic low-grade gliomas driven by KIAA1549:BRAF and familial low-grade gliomas associated with protein neurofibromin 1 (NF1), mTOR represents a central growth control target." (PMID 23717811, 2013). "These distinct mechanisms of mTOR activation notwithstanding, mTOR represents a promising therapeutic target in sporadic and NF1 associated low-grade gliomas." (PMID 23717811, 2013). "We report that coibamide A induces a rapid and sustained autophagic response via an mTOR-independent pathway, and is also a more potent and efficacious cytotoxic agent against human glioma cells than was previously appreciated." (PMID 23762328, 2013). "The downstream PI3K/Akt/mTOR pathway is one of the most important and best characterized pathways in gliomas." (PMID 23998913, 2013). "Dual PI3K/mTOR inhibitors are in clinical trials for adult high-grade gliomas and are poised to enter studies of pediatric tumors." (PMID 23717811, 2013). "Radiotherapy of primary glioma stem-like cells with CQ alone or in combination with a PI3K/mTOR inhibitor increased cell death." (PMID 24287492, 2013). "What seems specific for gliomas is activation of the mTOR pathway (mammalian target of rapamycin) by EGF via protein kinase C alpha, apparently through an independent circuit from the classical Akt-mTOR activation." (PMID 23998913, 2013). "The dual PI3K/mTOR inhibitor PI-103 was found to induce autophagy in therapy resistant glioma Inhibitors of autophagosome maturation cooperated with PI-103 to induce apoptosis through the mitochondrial pathway." (PMID 22680924, 2012). "H2O2 induces autophagy through interference with the beclin-1 and Akt/mTOR signaling pathways, and is regulated by the anti-apoptotic gene Bcl-2 in glioma U251 cells." (PMID 22363680, 2012). "Several of these mTOR inhibitors have been or are currently being tested in the clinical trials setting specifically in gliomas, including temsirolimus, everolimus (RAD001), and sirolimus." (PMID 22530121, 2012). "Lack of apoptosis and largely cytostatic effects have also been observed upon monotherapy with dual PI3K/mTOR inhibitors in conventional glioma lines." (PMID 23091617, 2012). "Another dual PI3K/mTOR inhibitor, PI-103, which is known to have monotherapy efficacy in glioma was recently shown to specifically reduce tumor volumes in combination with NSC-delivered s-trail in an orthotopic intracranial xenograft model." (PMID 22530121, 2012). "Western blot analysis of S6 phosphorylation protein suggested that mTOR pathway remains active after nutlin-3a in glioma cells." (PMID 21483692, 2011). "We next examined the biological consequences of inhibiting the PI3K/Akt/mTOR axis in PDGF-B driven gliomas." (PMID 21267448, 2011). "Our studies using primary glioma cultures from PTEN-deficient and PTEN-intact PDGF-B driven mouse GBMs demonstrate that PTEN status influences mTOR's sensitivity to Akt inhibition with perifosine." (PMID 21267448, 2011). "This compound was reported to have an IC50 of 1.3nM and 0.6nM against p110α and mTOR respectively, and displayed high anti-proliferative potency in U87 glioma tumour cells (IC50 = 5.3nM)." (PMID 21649578, 2011).
glioma (continued). "Previous studies using various cell lines, including glioma cell lines, have shown enhanced sensitivity of PTEN-deficient tumors to mTOR inhibition, which later was demonstrated to be due to Akt dependent regulation of Cyclin D1 and c-myc expression." (PMID 21267448, 2011). "In order to accurately dissect the role of PTEN in the sensitivity of gliomas to mTOR inhibition and Akt inhibition in vitro and in vivo, we utilized PDGF-B driven PTEN-deficient and PTEN-intact gliomas." (PMID 21267448, 2011). "Given the importance of Akt/mTOR signaling in glioma cell survival, significant efforts are being invested in identifying inhibitors that target this pathway." (PMID 20576128, 2010). "Taken together our studies suggest that (i) Iripallidal induces glioma cell apoptosis and (ii) inhibits Akt/mTOR and STAT3 pathway." (PMID 20576128, 2010). "Erlotinib has been combined with the dual-PI3K-mTOR inhibitor, PI-103, and demonstrated efficacy in PTEN mutant glioma compared to monotherapy or erlotinib with either PI3K inhibitor or mTOR inhibitor." (PMID 20515495, 2010). "There is a whole body of literature supporting the role of PTEN losses in activation of the PI3K/AKT/mTOR pathway in a variety of tumours including prostate, breast and glioma." (PMID 20664591, 2010). "Our studies suggest that Iripallidal induce apoptosis in glioma cells and inhibits the Akt/mTOR pathway." (PMID 20576128, 2010). "mTOR is emerging as a therapeutic target in human gliomas, and extending this to the paediatric setting will be facilitated by the use of these models for screening mTOR inhibitors, alone and in combination strategies." (PMID 19365568, 2009). "It has recently been described that cannabinoids promote endoplasmic reticulum stress and autophagy-mediated cell death in glioma cells through the Akt/mammalian target of rapamycin (mTOR) pathway inhibition and eIF2α activation." (PMID 19690545, 2009). "Moreover, inhibition of mTOR signaling can sensitize glioma cells to genotoxic stress, highlighting its relevance as a therapeutic target in both treatment-resistant and recurrent disease." (PMID 41301687, 2025). "Furthermore, based on the KEGG database, we discovered that CAMK2B can exert an influence on the growth and proliferation of glioma cells via the PI3K/AKT/mTOR signaling pathway." (PMID 41050075, 2025). "Specifically, E2F7 promotes tumorigenesis via EZH2-mediated PTEN/AKT/mTOR pathway in glioma." (PMID 41050080, 2025). "Moreover, NEAT1 stimulated glioma activity using modulating mTOR signalling, demonstrated in both in vivo and in vitro settings." (PMID 40387409, 2025). "While clinical trials of mTOR inhibitors in gliomas have so far shown limited efficacy, emerging data suggest these agents may ameliorate tumor-associated neurological dysfunction." (PMID 41301687, 2025). "Additionally, other gene mutations, for instance, BRAF variants have been implicated in enhancing epileptogenicity in gliomas while pathways, such as RAS/MAPK and PI3K/AKT/mTOR, play significant roles in both neuronal excitability and tumor growth." (PMID 40718831, 2025). "Similarly, it has also been suggested the PI3K/Akt/mTOR pathway is an effective therapeutic strategy in glioma." (PMID 39941886, 2025). "Critically, no prior study has investigated whether SERPINB6 modulates EMT in glioma through the PI3K/AKT/mTOR signalling pathway—a key driver of glioma." (PMID 40665565, 2025). "By inhibiting mTOR, metformin can slow the growth rate of glioma cells and may alter the immunogenicity of tumor cells, thus making them easier to recognize and attack by the immune system." (PMID 39944825, 2025). "The Akt/mTOR signaling pathway plays a crucial role in cell proliferation, stem cell maintenance, and tumorigenesis, and is typically found to be hyperactivated in gliomas." (PMID 40002794, 2025).
glioma (continued). "A previous study demonstrated the crucial role of YME1L within glioma cells in facilitating the transcription and expression of G protein subunit alpha i1 (Gαi1), a key protein essential for the activation of Akt-mTOR cascade through various receptor tyrosine kinases (RTKs) and non-RTK receptors." (PMID 38769124, 2024). "Various mTOR inhibitors have been investigated as anti-glioma therapies." (PMID 39794971, 2024). "Additionally, the potential of tetraspanin 8 to activate the mTOR signaling pathway represents a promising target for the development of anticancer therapies for gliomas." (PMID 39031113, 2024). "Targeting of mTOR and p70S6K signaling in cancers, including glioma, has met with limited success." (PMID 38714727, 2024). "Aberrant activation of the PI3K/Akt/mTOR pathway is a poor prognostic factor for gliomas." (PMID 39239650, 2024). "In MGMT promotor unmethylated glioma cells mTOR inhibition led to an induction of MGMT which may explain the protective effect despite the lack of effect on ROS levels in these cells." (PMID 38182566, 2024). "For example, THC inhibits AKT/mTOR, reducing the proliferation of glioma cells." (PMID 38396679, 2024). "Hence, our data indicate that PDZK1 acts as a tumorigenic gene in glioma by maintaining the activation of the AKT/mTOR signaling pathway." (PMID 38669103, 2024). "Consequently, we anticipate moderate mTOR activity and a higher autophagic rate in high-grade gliomas compared to low-grade ones." (PMID 39348350, 2024). "Notably, boosting Gαi1 expression through “oeGαi1” restored Akt-mTOR activation in YME1L-silenced glioma cells." (PMID 38769124, 2024). "In order to confirm the involvement of the RAS-RAF-MEK-ERK and PI3K-AKT/PKB mTOR pathways in the resistance of gliomas to the induction of programmed cell death, the first elements of these signaling pathways, i.e., RAF and PI3K, were blocked with specific siRNA." (PMID 38255833, 2024). "Notable pathways included MAPK signaling, cancer pathways, EGF/EGFR signaling, Glioblastoma signaling, Ras signaling, EGFR tyrosine kinase inhibitor resistance, miRs in cancer, PI3K-AKT signaling, p38 MAPK signaling, glioma, miRs in cardiomyocyte hypertrophy, and mTOR signaling." (PMID 39348350, 2024). "Inhibiting the Akt/mTOR signaling pathway triggers both autophagy and apoptosis in glioma cells." (PMID 38360888, 2024). "In gliomas, the activation of the mTOR pathway, mostly demonstrated in the immunohistochemical overexpression of various effectors, is highly present, but, for now, no extensive data link the Pi3K/AKT/mTor deregulation signature to a specific MAPK-pathway driver in high-grade and low-grade gliomas." (PMID 36831610, 2023). "The same study has also shown that the anti-tumoral effects of miR-15a and miR-92a are mediated by the downregulation of their direct targets Ccnd1 and Rap1b, respectively, thereby blocking the PI3K/AKT/mTOR signaling pathway, known to promote glioma invasion and migration." (PMID 38020906, 2023). "In addition, the relationship between ROS and PI3K/AKT/mTOR pathway leading to apoptosis following the treatment with this triple-drug combination was also investigated in glioma-induced rats." (PMID 37025487, 2023). "This indicates that safranal’s inhibitory effect on glioma is most likely to be achieved by inhibiting the PI3K/Akt/mTOR axis, acting on apoptosis-related proteins to increase tumour cell apoptosis, and acting on cycle-related proteins to regulate the tumour cell cycle." (PMID 37736545, 2023). "As for 4E-BP1, a mTOR independent regulation of this factor occurs in glioma cells, myoblasts, and acute myeloid leukemia, suggesting that 4E-BP1 activation could be regulated directly or indirectly by PI3K but not via Akt-mTORC1." (PMID 37047048, 2023). "In conclusion, all these data suggested that compound 1 treatment could inactivate EGFR/PI3K/Akt/mTOR signaling in glioma cells LN229." (PMID 37108310, 2023).